LGALS9 (galectin 9)
Description:
Binds galactosides. Has high affinity for the Forssman pentasaccharide. Ligand for HAVCR2/TIM3. Binding to HAVCR2 induces T-helper type 1 lymphocyte (Th1) death. Also stimulates bactericidal activity in infected macrophages by causing macrophage activation and IL1B secretion which restricts intracellular bacterial growth (By similarity). Ligand for P4HB; the interaction retains P4HB at the cell surface of Th2 T-helper cells, increasing disulfide reductase activity at the plasma membrane, altering the plasma membrane redox state and enhancing cell migration. Ligand for CD44; the interaction enhances binding of SMAD3 to the FOXP3 promoter, leading to up-regulation of FOXP3 expression and increased induced regulatory T (iTreg) cell stability and suppressive function (By similarity). Promotes ability of mesenchymal stromal cells to suppress T-cell proliferation. Expands regulatory T-cells and induces cytotoxic T-cell apoptosis following virus infection. Activates ERK1/2 phosphorylation inducing cytokine (IL-6, IL-8, IL-12) and chemokine (CCL2) production in mast and dendritic cells. Inhibits degranulation and induces apoptosis of mast cells. Induces maturation and migration of dendritic cells. Inhibits natural killer (NK) cell function. Can transform NK cell phenotype from peripheral to decidual during pregnancy. Astrocyte derived galectin-9 enhances microglial TNF production (By similarity). May play a role in thymocyte-epithelial interactions relevant to the biology of the thymus. May provide the molecular basis for urate flux across cell membranes, allowing urate that is formed during purine metabolism to efflux from cells and serving as an electrogenic transporter that plays an important role in renal and gastrointestinal urate excretion (By similarity). Highly selective to the anion urate (By similarity). [Isoform 2]: Acts as an eosinophil chemoattractant. It also inhibits angiogenesis. Suppresses IFNG production by natural killer cells (By similarity).
Synonyms: LGALS9A; HUAT
Tractability: Small molecule: a structure with a bound ligand is known; a high-quality ligand is known. Antibody: UniProt places it where antibodies can reach, with high confidence; its Gene Ontology location is reachable by antibodies, with medium confidence. PROTAC: ubiquitination databases record sites on it; its protein half-life has been measured; a small molecule that binds it is known.
Target class: Other cytosolic protein
Gene: Protein-coding gene on chromosome 17 (27,629,798 to 27,649,561, forward strand). Ensembl gene ENSG00000168961.
Subcellular location: Cytoplasm; Nucleus; Secreted; Secreted (Isoform 2); Secreted (Isoform 3)
Subcellular location (Human Protein Atlas): Cytosol; Predicted to be secreted
Pathways (Reactome):
Immune System: Interleukin-2 family signaling
Gene Ontology:
Molecular function: carbohydrate binding; disaccharide binding; enzyme binding; oligosaccharide binding; receptor ligand activity; galactose binding; galactoside binding
Biological process: cellular response to type II interferon; cellular response to virus; ERK1 and ERK2 cascade; female pregnancy; immune response; inflammatory response; maternal process involved in female pregnancy; mature conventional dendritic cell differentiation; natural killer cell tolerance induction; negative regulation of activated T cell proliferation; negative regulation of CD4-positive, alpha-beta T cell proliferation; negative regulation of chemokine production; negative regulation of gene expression; negative regulation of mast cell degranulation; negative regulation of natural killer cell mediated cytotoxicity; negative regulation of T-helper 1 type immune response; negative regulation of tumor necrosis factor production; negative regulation of type II interferon production; NK T cell activation; p38MAPK cascade; positive regulation of activated T cell autonomous cell death; positive regulation of canonical NF-kappaB signal transduction; positive regulation of CD4-positive, alpha-beta T cell proliferation; positive regulation of dendritic cell apoptotic process; positive regulation of dendritic cell chemotaxis; and 31 more
Cellular component: cytoplasm; cytosol; extracellular matrix; extracellular region; nucleus
Genetic constraint (gnomAD): Loss-of-function variants: 23 observed, 32.02 expected, observed/expected ratio (o/e) 0.72, 90% interval 0.52 to 1.02. The upper end of that interval is the gene's LOEUF score, 1.02, which puts it in group 4 of 6, group 1 being the genes least tolerant of losing a copy. Missense variants: 329 observed, 409.55 expected, observed/expected ratio (o/e) 0.8, 90% interval 0.73 to 0.88. Synonymous variants: 141 observed, 163.95 expected, observed/expected ratio (o/e) 0.86, 90% interval 0.75 to 0.99.
Homologues: Orthologues: chimpanzee LGALS9 (99% identical), dog LGALS9 (67% identical), Caenorhabditis elegans lec-1 (28% identical), Caenorhabditis elegans lec-12 (28% identical), Caenorhabditis elegans lec-3 (28% identical), Caenorhabditis elegans F40H6.5 (27% identical), Drosophila melanogaster galectin (27% identical), Drosophila melanogaster CG11374 (21% identical), zebrafish lgals3b (20% identical), Caenorhabditis elegans C27C7.5 (19% identical), Drosophila melanogaster CG13950 (17% identical), Caenorhabditis elegans lec-6 (15% identical), and 13 more. Paralogues in human: LGALS9B (95% identical), LGALS9C (94% identical), LGALS4 (36% identical), LGALS8 (31% identical), LGALS12 (27% identical), LGALS3 (23% identical), LGALSL (17% identical), LGALS7 (15% identical), LGALS7B (15% identical), LGALS1 (12% identical), GRIFIN (10% identical), LGALS2 (10% identical), and 4 more.
Diseases named in the same sentence as LGALS9 in open-access papers:
LGALS9 is named in the same sentence as 330 diseases in open-access papers, as found by Europe PMC text mining. Sharing a sentence is not in itself a finding about the gene and the disease. The quoted sentences say what the papers report.
melanoma (58 papers, 2012 to 2025). A malignant, usually aggressive tumor composed of atypical, neoplastic melanocytes. "•LGALS9 was upregulated in melanoma-derived samples, and higher expression is also linked with melanoma prognosis." (PMID 41271007, 2025). "This study aimed to investigate the association of TIM-3 and LGALS9 DNA methylation with gene expression, patients’ survival, as well as molecular and immune correlates in malignant melanoma." (PMID 31747929, 2019). "In melanoma cells, galectin-9 was able to induce cell aggregation and apoptosis, and down-regulation of Gal-9 was associated with distant metastasis." (PMID 29361803, 2018). "Galectin-9, a β-galactoside-binding lectin, is closely associated with reduced metastasis and low recurrence in patients with malignant melanoma." (PMID 28060744, 2017). "Moreover, higher levels of LGALS9 protein in LN tissue are associated with poor overall survival of melanoma patients (p = 0.0018)." (PMID 41271007, 2025). "Additional 3D migration assays in the presence of melanoma tumor spheroids were performed to investigate how galectin-9 depletion alters DC function in a physiologically relevant setup." (PMID 40986321, 2025). "Exposure of mature cDC2s to melanoma-derived CM led to the downregulation of surface galectin-9 and CCR7 expression levels." (PMID 40986321, 2025). "The UL16 binding protein 2 and 3 (Ulbp2/3), carcinoembryonic antigen‐related cell adhesion molecule 1 (Ceacam1) and galectin 9 (LgalS9) were identified as possible regulators of melanoma cell resistance to NK‐cell cytotoxicity." (PMID 41078003, 2025). "On the other hand, galectin- 9 has also been reported to suppress metastasis in melanoma and colon carcinoma mice models." (PMID 38195762, 2024). "On the other hand, in mouse models of melanoma and colon cancer, galectin-9 suppresses tumor metastasis by inhibiting tumor cell adhesion to extracellular matrices and endothelium." (PMID 35008740, 2021). "Research into other tumor types showed a consistent pattern, as galectin-9 suppressed migration and invasion in various tumors studied such as hepatocellular carcinoma, melanoma, colon cancer, and gastric cancer." (PMID 35008740, 2021). "Galectin-9 expressed in melanoma cells binds to TIM-3 on Tregs, promoting tumor progression in the mouse or human melanoma tissues." (PMID 34806028, 2021). "A dynamic modulation of immune suppressive ICM such as PD-L1, PD-L2, HVEM and Galectin-9 (only on B16 melanoma) and immune stimulatory ICM like ICOS-L, CD137-L, Ox40-L, and CD27-L on both murine and human cancer cells was observed." (PMID 34201238, 2021). "In breast, pancreatic cancer and melanoma, expression of galectin-9 correlates with good prognosis for those patients." (PMID 32063906, 2020). "Of note, CpG site 13 showed increased LGALS9 methylation in CD8+ T cells not only compared to melanoma and melanocyte cell lines but also compared to distinct leukocytes including the CD4+ T lymphocytes." (PMID 31747929, 2019). "In the present study, we provide a comprehensive overview of DNA methylation of TIM-3 and its ligand LGALS9 in melanomas, melanocytes, and immune cells." (PMID 31747929, 2019). "In almost all solid cancers, galectin-9 expression was found to be decreased in cancerous tissues, except for oral and pancreatic cancer and melanoma." (PMID 29179486, 2017). "In particular, lower levels of galectin-9 have been observed in most types of cancer cells, including oral squamous cell carcinoma, melanoma, breast cancer and gastric cancer, than in their normal counterparts." (PMID 27028892, 2016). "Interestingly, the increased expression of LGALS9 in LN was also correlated with reduced overall survival in melanoma patients in the Cero dataset (p = 0.0018)." (PMID 41271007, 2025). "Interestingly, higher levels of LGALS9 in the LN tissues also correlated with lower overall survival in melanoma patients, based on the Cero dataset data (p = 0.0018)." (PMID 41271007, 2025).
melanoma (continued). "A role for VEGF-C in inducing CCL21/CCR7-mediated lymphangiogenesis of melanoma cells was noted and a low percentage of melanoma cells expressed the immune checkpoint ligands, PD-L1 and galectin-9, resulting in cancer stem cell characteristics and increased metastasis." (PMID 35203305, 2022). "Tumor-associated Treg cells, which emphasize inhibitory checkpoint receptor Tim-3, comprise a particular subset of tissue Treg cells by promoting tumor progression in mouse or human melanoma tissues by binding to galectin-9 which is expressed in melanoma cells." (PMID 33936081, 2021). "Reports on the epigenetic regulation of TIM-3 and LGALS9 in melanoma are sparse." (PMID 31747929, 2019). "Thus, the galectin-9 expression level was correlated with cellular adhesion and aggregation in melanoma cells, oral squamous cell carcinomas, breast cancer and hepatocellular carcinoma (HCC)." (PMID 29389859, 2018). "In contrast to the paraffin-sections, all melanoma cell lines expressed intracellular galectin-9." (PMID 22347406, 2012). "In summary, B cells in melanoma lesions are polarized to express regulatory cytokines, including TGF-β, and may engage in immunosuppressive crosstalk with tumor-associated T cells via Galectin-9 signaling." (PMID 35909944, 2022). "Similarly, mammalian galectin-9 suppressed binding of HA to CD44 on melanoma and colon cancer cell lines resulted in suppression of both attachment and invasion of tumor cells by inhibiting their binding of adhesive molecules to ligands on vascular endothelium and the extracellular matrix." (PMID 36032131, 2022). "Furthermore, research has indicated that primary melanoma lesions and melanocytic nevi have high expression of LGALS9, but the minimal expression is found in metastatic melanoma lesions due to the tumor-suppressor function of LGALS9, which inhibits metastatic progression." (PMID 32903590, 2020). "Additionally, the following studies further demonstrated that administration of galectin-9 in mice suppresses lung metastasis of melanoma cells via inhibition of the binding of adhesive molecules on tumor cells to ligands on vascular endothelium and extracellular matrix." (PMID 29389859, 2018). "High levels of CD38, LGALS9, and TNC were found in the sinuses of the lymph node, supporting potential immunological targets for the PMN in melanoma." (PMID 41271007, 2025). "We detected upregulated LGALS9 (p = 0.029) and CD38 (p = 0.14) in the sEV cargoes in the blood plasma sEVs of melanoma patients than in healthy donors." (PMID 41271007, 2025). "In BR1, we also observed enrichment of the LGALS9 axis, known to induce MHC-II expression on macrophages and DCs and strong anti-tumor responses in murine melanoma models." (PMID 39372744, 2024). "Upregulation of galectin-9 expression was found in immune cells, tumor cells, and blood plasma of PDAC and melanoma patients." (PMID 36873388, 2023). "Between 1 and 5% of melanoma cells per cell line was identified as highly CCR7 positive co-expressed with two immune checkpoint ligands, PD-L1 and galectin-9, and had cancer stem cell characteristics." (PMID 35203305, 2022). "Thirdly, we compared the methylation status of HAVCR2/TIM-3 and LGALS9 with isolated monocytes, granulocytes, B cells, CD8+ T cells, and CD4+ T cells from healthy donors and melanocyte and melanoma cell lines." (PMID 31747929, 2019). "Furthermore, the upregulation of key melanoma-specific cargoes: LGALS9 (p = 0.029), CD3D (p = 0.097), and CD38 (p = 0.14) in the blood plasma sEVs of melanoma patients was noted in contrast to healthy donors." (PMID 41271007, 2025). "The proteins CD38, LGALS9, and TNC were selected for evaluation to determine whether lymphatic sinuses in melanoma patients exhibit elevated levels of these proteins compared with control LN sinuses." (PMID 41271007, 2025).
melanoma (continued). "For example, studies in non-CNS cancers have shown that high expression of Galectin-9 was correlated with an improved outcome for patients diagnosed with breast cancer, melanoma, HCC, colon cancer, as well as bladder urothelial carcinoma." (PMID 38523840, 2024). "Galectin-9 interacts with cell surface adhesive molecule CD44 and this interaction inhibits the complex formation of CD44 with hyaluronic acid, which consequently attenuates metastatic dissemination of melanoma and colon cancer cells." (PMID 36873388, 2023). "In addition, the LGALS9-HAVCR2 ligand–receptor pair is an important target for mediating immune escape in various cancers, including leukemia, breast cancer, and melanoma." (PMID 37874419, 2023). "TGF-β-expressing B cells in the melanoma tumor microenvironment assembled in clusters and interacted with T cells via lymphoid recruitment (SELL, CXCL13, CCL4, CD74) signals and with Tregs via CD47:SIRP-γ, and FOXP3-promoting Galectin-9:CD44." (PMID 35909944, 2022). "Viable melanoma cells cannot be retrieved after enzymatic digestion in this mouse model, therefore we could not determine the expression of PD-L1 and/or galectin-9 on the surface of tumor cells." (PMID 33408092, 2021). "It was reported that galectin-9 treatment could expand the population of unique macrophages with a plasmacytoid cell-like phenotype, and therefore promotes NK cell-mediated anti-tumor activity and significantly prolongs the survival of B16F10 melanoma-bearing mice." (PMID 28060744, 2017). "•Melanoma-negative sentinel lymph node carries more contents of the sEV cargoes, CD38, LGALS9 (galectin-9), and TNC (tenascin-C), in the lymphatic sinuses compared with control lymph nodes." (PMID 41271007, 2025). "Similarly, IL1B was expressed at much higher levels in iCAFs derived from melanoma, while TGFB3 and LGALS9 were strongly expressed in iCAFs from BCC and SCC but not melanoma." (PMID 39516494, 2024). "LGALS9, which has been shown to interact with CD40 on T cells thereby attenuating their expansion and effector function, was strongly expressed in CAFs from BCC and SCC but not melanoma." (PMID 39516494, 2024).
breast carcinoma (57 papers, 2010 to 2026). "Our analysis indicates that KIT mutations correlate with elevated serum levels of galectin-9 in patients with breast cancer." (PMID 38927753, 2024). "This study found a significant correlation between a cancer-critical KIT mutation and higher serum galectin-9 levels in breast cancer patients, similar to other studies." (PMID 38927753, 2024). "In contrast, others found that galectin-9 is associated with worse clinical outcomes in patients with breast cancer, renal cancer, gastric cancer, and lung cancer." (PMID 37174080, 2023). "Possible reasons underlying such an activity were suggested to be galectin-9-induced cell aggregation and reduced adhesion of breast cancer cells to the extracellular matrix." (PMID 31354733, 2019). "In clinical studies, an association of the expression level of galectin-9 with tumor metastasis has been established in breast cancer and in HCC." (PMID 29389859, 2018). "LGALS9 has previously been associated with antimetastatic potential in breast cancer, potentially indicating a compensation for increased chromosomal instabilility which may drive metastasis." (PMID 37919776, 2023). "Whereas high galectin-9 expression was associated with reduced survival in lung cancer, increased expression was associated with improved survival in hepatocellular carcinoma, gastric and colorectal cancer and also with a low metastatic potential in breast cancer." (PMID 32055023, 2020). "Our findings indicate that TIM-3 and its binding partner galectin-9 represent alternative (or additional) targets in breast cancer patients." (PMID 37174080, 2023). "Specifically, CD112, TNFSF4, TNFSF18, and LGALS9 were significantly overexpressed in breast carcinomas, strongly suggesting potent and valuable effects." (PMID 34545132, 2021). "One of the emerging immune checkpoint molecules is the T-cell immunoglobulin mucin-3 (Tim-3)/Galectin-9 (Gal-9) checkpoint, viewed as a promising target for the treatment of breast cancer, bladder cancer and others." (PMID 34944985, 2021). "The whole pathway includes activation of HIF-1 which upregulates TGF-β expression; TGF-β is then secreted and displays autocrine activity leading to the induction of galectin-9 expression in MCF-7 breast cancer cells." (PMID 33295886, 2020). "In breast carcinoma, liver cancer, and cervical tumors, LGALS9 expression affects disease prognosis." (PMID 33381555, 2020). "For example presence of TALL-104 cells significantly upregulates galectin-9 surface presence in MCF-7 breast cancer cells." (PMID 31354733, 2019). "Surface-based galectin-9 was able to protect breast carcinoma cells against cytotoxic T cell-induced death." (PMID 31354733, 2019). "MCF-7, BC-8701, and MDA-MB-231 breast cancer cells all expressed Tim-3, galectin-9, FLRT3, and at least one LPHN isoform." (PMID 31354733, 2019). "Breast cancer cells were unable to secrete galectin-9, but were capable of maintaining its cell surface expression." (PMID 31354733, 2019). "Levels of soluble Tim-3 were also downregulated in blood plasma of breast cancer patients which is in line with galectin-9 values." (PMID 31354733, 2019). "Based on these observations, it can be concluded that the FLRT3-LPHN-Tim-3-galectin-9 pathway is functional in other cancer cells and in particular in breast cancer cell lines and primary tumors." (PMID 31354733, 2019). "Patients with galectin-9 negative breast cancers showed high potential with distant metastases and correlated with higher histopathologic grades when compared with patients with galectin-9 positive breast cancer." (PMID 29389859, 2018). "Galectin-9 contributes to the aggregation of breast cancer cells and the relation between galectin-9 expression in tumor tissue and distant metastasis in patients with breast cancer was demonstrated." (PMID 23658855, 2010). "Kinome analysis of breast cancer cells has suggested that Galectin-9 can undergo phosphorylation." (PMID 38815863, 2024).